DPH6 (diphthamine biosynthesis 6)
Description:
Amidase that may catalyze the last step of diphthamide biosynthesis using ammonium and ATP. Diphthamide biosynthesis consists in the conversion of an L-histidine residue in the translation elongation factor (EEF2) to diphthamide (By similarity).
Synonyms: ATPBD4; MGC14798
Tractability: PROTAC: ubiquitination databases record sites on it; its protein half-life has been measured.
Gene: Protein-coding gene on chromosome 15 (35,217,345 to 35,546,193, reverse strand). Ensembl gene ENSG00000134146.
Subcellular location (Human Protein Atlas): Nucleoli; Nucleoli rim; Nucleoplasm
Pathways (Reactome):
Metabolism of proteins: Synthesis of diphthamide-EEF2
Gene Ontology:
Molecular function: diphthine-ammonia ligase activity
Biological process: protein histidyl modification to diphthamide
Cellular component: cytosol
Genetic constraint (gnomAD): Loss-of-function variants: 23 observed, 23.29 expected, observed/expected ratio (o/e) 0.99, 90% interval 0.71 to 1.4. The upper end of that interval is the gene's LOEUF score, 1.4, which puts it in group 5 of 6, group 1 being the genes least tolerant of losing a copy. Missense variants: 286 observed, 251.08 expected, observed/expected ratio (o/e) 1.14, 90% interval 1.03 to 1.26. Synonymous variants: 98 observed, 83.82 expected, observed/expected ratio (o/e) 1.17, 90% interval 0.99 to 1.38.
Homologues: Orthologues: chimpanzee DPH6 (99% identical), pig DPH6 (95% identical), rabbit DPH6 (93% identical), dog DPH6 (93% identical), macaque DPH6 (93% identical), mouse Dph6 (88% identical), rat Dph6 (86% identical), guinea pig DPH6 (76% identical), tropical clawed frog dph6 (72% identical), zebrafish dph6 (68% identical), Drosophila melanogaster CG1578 (57% identical), Caenorhabditis elegans dph-6 (55% identical).
Diseases named in the same sentence as DPH6 in open-access papers:
DPH6 is named in the same sentence as 7 diseases in open-access papers, as found by Europe PMC text mining. Sharing a sentence is not in itself a finding about the gene and the disease. The quoted sentences say what the papers report.
lung carcinoma (1 paper, 2019). "DPH6 has not been previously associated with lung cancer, and further studies are warranted to confirm the present findings." (PMID 31450665, 2019).
cancer (2 papers, 2019 to 2020). A tumor composed of atypical neoplastic, often pleomorphic cells that invade other tissues. "Thus, as very little is known about ABHD17A and DPH6 in the context of cancer, it is difficult to precisely speculate how they may be playing a role in tumor cell extrinsic regulation of metastatic colonization." (PMID 32245826, 2020).
DPH6 also shares sentences with these, for which no sentence is quoted: adenocarcinoma (1 paper); Autoimmunity (1); colorectal cancer (1); pancreatic cancers (1); tumor (1).